SOX2-OT (SOX2 overlapping transcript)
Diseases named in the same sentence as SOX2-OT in open-access papers (continued):
Sharing a sentence is not in itself a finding about the gene and the disease.
bladder cancer (6 papers, 2020 to 2023). "This study is the first to demonstrate that SOX2OT plays an important regulatory role in BCSCs and that SOX2OT may serve as a potential diagnostic biomarker and therapeutic target in bladder cancer." (PMID 32019566, 2020). "It has been reported that SOX2OT inhibition can restrict the bladder cancer stem cell (CD44+, ALDH1+) self-renewal and cisplatin resistance by SOX2 regulation." (PMID 36548179, 2022). "SOX2OT expression was upregulated in 71.7% (76/106) of bladder cancer tissues compared with in the corresponding normal tissue samples." (PMID 32019566, 2020). "Mechanistically, we found that SOX2OT expression positively correlated with SOX2 expression in bladder cancer, and SOX2OT knockdown inhibited SOX2 expression in BCSCs." (PMID 32019566, 2020). "Overexpressed lncRNA SOX2OT in bladder cancer is positively correlated with a high histological grade, advanced TNM stage, and poor prognosis." (PMID 33288752, 2020). "SOX2OT was highly expressed in bladder cancer, and increased SOX2OT expression was positively correlated with a high histological grade, advanced TNM stage and poor prognosis." (PMID 32019566, 2020). "In the present study, we showed that SOX2OT expression was significantly upregulated in bladder cancer tissues compared with in the corresponding normal tissues, and its expression was significantly correlated with histological grade, TNM stage and prognosis." (PMID 32019566, 2020). "In this study, we found that SOX2OT expression was significantly upregulated in bladder cancer tissues compared with in the corresponding normal tissues, and increased SOX2OT expression was positively correlated with an advanced TNM stage, high histological grade and poor prognosis." (PMID 32019566, 2020). "However, the clinical significance and biological function of SOX2OT in bladder cancer are completely unknown." (PMID 32019566, 2020). "However, the clinical significance and molecular mechanism of SOX2OT in bladder cancer are still unknown." (PMID 32019566, 2020). "Our study revealed that SOX2OT functions as a miRNA sponge to positively regulate the expression of SOX2 by sponging miR-200c and subsequently promoting the stemness phenotype of BCSCs, thus playing an oncogenic role in bladder cancer pathogenesis." (PMID 32019566, 2020). "Accumulating evidence has indicated that SOX2OT plays a key role in the transcriptional regulation of the SOX2 gene and that SOX2 is a marker for stem-like tumour cells in bladder cancer, suggesting that SOX2OT may play an important regulatory role in BCSCs." (PMID 32019566, 2020). "SOX2OT functions as a miRNA sponge to positively regulate SOX2 expression by sponging miR-200c and subsequently promotes the stemness phenotype of BCSCs, thus playing an oncogenic role in bladder cancer pathogenesis." (PMID 32019566, 2020). "SOX2OT and SOX2 expression levels were significantly upregulated in BCSCs compared with bladder cancer non-stem cells (BCNSCs)." (PMID 32019566, 2020).
gastric cancer (6 papers, 2017 to 2021). A primary or metastatic malignant neoplasm involving the stomach. "The lncRNA SOX2OT is a recognized oncogene in many human carcinomas such as colorectal and gastric cancer, and RT-PCR results indicated that SOX2OT transcript expression is also elevated in ES cell lines." (PMID 34440137, 2021). "Recent research has shown that the overexpression of SOX2OT is correlated with aggressive tumor behavior in gastric cancer." (PMID 31827385, 2019). "SOX2OT is increased in gastric cancer tissues and cells, and has become a biological marker of poor prognosis for gastric cancer." (PMID 29132362, 2017). "For studies evaluating OS in different type of cancer, the results suggested that promoted SOX2OT levels could estimate worse outcome in gastric cancer (HR = 2.30, 95% CI: 1.52–3.47, P<0.0001)." (PMID 28489861, 2017). "It has been reported that SOX2OT expression is correlated with TNM stage, metastasis and prognosis of hepatocellular carcinoma and gastric cancer." (PMID 29849506, 2018).
Alzheimer disease (4 papers, 2020 to 2023). A progressive, neurodegenerative disease characterized by loss of function and death of nerve cells in several areas of the brain leading to loss of cognitive function such as memory and language. "Our results are consistent with those of previous research, which associated SOX2OT overexpression with neurocognitive dysfunction in Alzheimer’s disease." (PMID 37098623, 2023). "Other lncRNAs, such as BC200 and Sox2OT, were found to be associated with Alzheimer’s disease or Parkinson’s disease." (PMID 34198485, 2021). "In an Alzheimer’s disease model, lncRNA SOX2OT transcription was accompanied by SOX2 gene expression and associated with cognitive dysfunction." (PMID 37098623, 2023).
hepatocellular carcinoma (3 papers, 2017 to 2018). A malignant tumor that arises from hepatocytes. "Separate studies have reported that expression of SOX2 and SOX2OT in hepatocellular carcinoma is each associated with poor prognosis." (PMID 28388544, 2017). "SOX2 and SOX2OT are also likely to be co-expressed in hepatocellular carcinoma." (PMID 28388544, 2017).
osteosarcoma (3 papers, 2018 to 2023). A usually aggressive malignant bone-forming mesenchymal neoplasm, predominantly affecting adolescents and young adults. "In order to explore the biological function of SOX2OT V7 in osteosarcoma, V7 gain-of-function OS cell models were established by V7 overexpressed lentivirus infection." (PMID 29475441, 2018). "One of the approaches to decrease the expression of SOX2OT in GBM cells might be to test different bioactive compounds, given that successful targeting of SOX2OT transcript variant 7 with EGCG, a polyphenol in green tea, has already been demonstrated in osteosarcoma cells." (PMID 37047365, 2023). "EGCG could inhibit SOX2OT V7 which is closely related to pluripotency regulator SOX2 of CSCs, therefore, we speculated that EGCG would exert certain inhibitory effect on osteosarcoma stem cells (OSCs)." (PMID 29475441, 2018).
Sepsis (3 papers, 2020 to 2023). Sepsis is defined as life-threatening organ dysfunction caused by a dysregulated host response to infection. "It has been demonstrated that by suppressing the expression of Sox2OT in mice, sepsis-induced deficits in hippocampal neurogenesis and cognitive function were improved." (PMID 37630804, 2023). "We found that sepsis activated SOX2OT in the hippocampus, and SOX2OT knockdown attenuated sepsis-induced deficits in hippocampal neurogenesis and cognitive function." (PMID 33100215, 2020). "SOX2OT knockdown attenuated sepsis-induced neurogenesis impairment and cognitive dysfunction, likely through its effects on downstream SOX2 signaling." (PMID 33100215, 2020). "In addition, in a sepsis model, the activation of SOX2OT in the mouse hippocampus led to defects in hippocampal neurogenesis and cognitive function, whereas the knockdown of SOX2OT alleviated these symptoms." (PMID 37098623, 2023). "Furthermore, our data suggest that sepsis upregulates the transcription factor OCT4 through the SOX2OT/SOX2 axis." (PMID 33100215, 2020). "Moreover, we found that SOX2 knockdown reduced sepsis-induced hippocampal neurogenesis and cognitive dysfunction, similar to the beneficial effects of SOX2OT knockdown." (PMID 33100215, 2020). "Thus, inhibiting the signaling pathway involving Sox2OT and SOX2 may hold promise as a potential therapeutic approach for treating or preventing neurological damage associated with sepsis-induced encephalopathy." (PMID 37630804, 2023). "Therefore, we sought to examine here whether lncRNA SOX2OT may be involved in sepsis-induced hippocampal neurogenesis and cognitive dysfunction in a mouse model." (PMID 33100215, 2020). "First, our data demonstrated that sepsis induced by CLP surgery led to cognitive dysfunction and upregulation of SOX2OT and SOX2." (PMID 33100215, 2020).
lymph node metastasis (2 papers, 2017 to 2018). "Higher levels of serum SOX2OT were remarkably correlated with lymph node metastasis (P < 0.05)." (PMID 29504701, 2018).
pancreatic ductal adenocarcinoma (2 papers, 2020 to 2021). An infiltrating adenocarcinoma that arises from the epithelial cells of the pancreas. "However, the expression pattern and mechanism of SOX2OT in pancreatic ductal adenocarcinoma have not been fully elucidated." (PMID 34552054, 2021).
colorectal tumor (1 paper, 2021). "To investigate the expression of SOX2OT in human CRC, we first analyzed SOX2OT in 28 paired colorectal tumor tissues." (PMID 33993197, 2021).
diabetes (1 paper, 2018). "Inhibition of Sox2OT was found to protect high glucose-induced RGCs in vitro and appeared to play a neuroprotective role in diabetes-related retinal neurodegeneration in vivo." (PMID 29915562, 2018). "Thus, Sox2OT knockdown may be a potential treatment option for diabetes-induced retinal neurodegeneration." (PMID 29915562, 2018).
esophageal cancer (1 paper, 2022). A primary or metastatic malignant neoplasm involving the esophagus. "Regarding the reported association between the SOX2 and SOX2OT, we aimed to investigate the expression and function of SOX2OT as a lncRNA in tumorspheres derived from esophageal cancer cells (YM1, KYSE30)." (PMID 36548179, 2022).
Hyperglycemia (1 paper, 2020). An increased concentration of glucose in the blood. "In addition, SOX2OT knockdown in adult mice can protect against hyperglycemia-induced retinal neurodegeneration." (PMID 33100215, 2020).
lung squamous cell carcinoma (1 paper, 2015). "SOX2OT and SOX2 co-upregulation has been reported in lung tumor tissues, particularly in squamous cell lung carcinoma, which is related to 3q26.33 genomic amplification." (PMID 26136768, 2015).
Miscarriage (1 paper, 2019). A pregnancy that ends at a stage in which the fetus is incapable of surviving on its own, defined as the spontaneous loss of a fetus before the 22th week of pregnancy. "Therefore, we investigated the relationship between the lncRNA SOX2OT rs9839776 C>T polymorphism and recurrent miscarriage susceptibility." (PMID 31827385, 2019). "We speculated that the rs9839776 polymorphism may increase the susceptibility to recurrent miscarriage by regulating the expression of SOX2OT." (PMID 31827385, 2019). "However, we do not have to detect the expression level of SOX2OT in recurrent miscarriage patients." (PMID 31827385, 2019).
pancreatic cancer (1 paper, 2021). "In our previous study, we found that the expression of lncRNA SOX2OT was upregulated in pancreatic cancer, and it was associated with poor prognosis of pancreatic cancer patients." (PMID 34552054, 2021). "We have previously demonstrated that SOX2OT is upregulated in pancreatic cancer tissues and is associated with poor prognosis in pancreatic cancer patients." (PMID 34552054, 2021). "In vitro study results have shown that overexpression of SOX2OT may lead to the malignant proliferation of pancreatic cancer cells." (PMID 34552054, 2021). "SOX2OT regulates the levels of a large number of mRNAs through modulating FUS in pancreatic cancer." (PMID 34552054, 2021). "We also explored the specific regulatory mechanism of SOX2OT and its downstream protein FUS in pancreatic cancer cell migration and invasion." (PMID 34552054, 2021). "To determine whether the regulation of FUS protein by SOX2OT affects the migration and invasion of pancreatic cancer cells, we reversed the regulation of FUS protein by SOX2OT using ectopic expression of FUS." (PMID 34552054, 2021). "In conclusion, SOX2OT may bind to FUS protein to promote its degradation via ubiquitination, thereby promoting cell proliferation, migration, and invasion, then affecting the development of pancreatic cancer." (PMID 34552054, 2021).
pulmonary arterial hypertension (1 paper, 2023). Pulmonary arterial hypertension (PAH) is a group of diseases characterized by mean pulmonary artery pressure >20 mmHg and elevated pulmonary arterial resistance leading to right heart failure. "SOX2OT (SOX2 Overlapping Transcript): Although the role of SOX2OT in pulmonary arterial hypertension (PAH) has been examined, its implications in CRC and the tumor microenvironment are still unexplored." (PMID 37760852, 2023).
cancer (32 papers, 2014 to 2025). A tumor composed of atypical neoplastic, often pleomorphic cells that invade other tissues. "LncRNA SOX2 Overlapping Transcript (Sox2OT) is highly expressed in several cancers and has been associated with unfavorable prognosis in those cancers where it was found to promote migration and invasion through diverse mechanisms." (PMID 35455947, 2022). "The mechanism underlying the relationship between elevated SOX2OT expression and poor prognosis in cancer patients need to be further elucidated." (PMID 28489861, 2017). "Further analysis revealed that the deregulated lncRNAs in ESCC included many well-known tumor-associated lncRNAs, such as H19, TUG1 and SOX2OT, which have been reported to contribute to tumorigenicity in other cancers." (PMID 28854977, 2017). "For example, miR-10a-5p and lncRNA-SOX2 overlapping transcript (lncRNA-SOX2OT) are cargo molecules in EVs derived from cancer-associated fibroblasts (CAFs) and invasive cancer cells, respectively, enhancing the metastatic capacity of circumjacent cancer cells." (PMID 33435156, 2021). "Our results propound SOX2OT association with cell cycle and mitosis regulation in cancer cells." (PMID 30202240, 2018). "Six genes—HFE2, LOC339674, SERINC2, SFTA3, SOX2OT, and ACPP—emerged as the most promising candidates, supported by enrichment and survival associations across multiple cancers." (PMID 41408184, 2025). "Upregulation of DANCR and SOX2OT in PTC was observed to correlate with cancer onset, and cancer onset and progression, respectively." (PMID 38785786, 2024). "In vitro and in vivo studies have proved that SOX2OT regulates the proliferation and differentiation of CSCs and is involved in the multidrug resistance and metastasis of cancer cells." (PMID 37149646, 2023). "Different studies have reported upregulation of the SOX2OT in solid tumors including breast, lung, ovarian, hepatocellular, colorectal, and esophageal carcinoma." (PMID 36548179, 2022). "In some somatic cancers, the dysregulation of SOX2OT expression and its concomitant expression with SOX2 has become a prominently observed phenomenon, and SOX2OT plays a key role in pluripotency and tumorigenesis." (PMID 31827385, 2019). "Previously in our laboratory, we observed that SOX2OT inhibition can significantly decrease lung and brain (un-published yet) cancer cell colony formation ability with a minor cell cycling disturbance." (PMID 30202240, 2018). "This novel potential function of SOX2OT promises new insights in cancer therapies; however more investigation is necessary to clear the underlying mechanism of SOX2OT relevance to mitotic cell cycle regulation or embryonic development." (PMID 30202240, 2018). "A total of 5 studies including 421 patients were included in this study, and the results suggested that promoted SOX2OT expression was significantly correlated with poor prognosis and tumor progression in patients with various types of cancer." (PMID 28489861, 2017). "A statistically significant correlation coefficient between SOX2 and SOX2OT in cancer tissues, suggested the possibility of SOX2OT role in the regulation of SOX2 expression." (PMID 26136768, 2015). "Moreover, a higher SOX2OT level is associated with worse outcomes, including increased TAMR cancer cell proliferation, invasion, and migration." (PMID 38649821, 2024). "Ma-L and associates found that in ES clinical samples, just like in most other cancers, Sox2OT lncRNA is highly expressed and contributes to its malignant behavior by sponging miR-363, thereby causing overexpression of FOXP4 protein levels to promote several downstream malignancy-inducing pathways." (PMID 35455947, 2022). "It has been reported that SOX2OT inhibition can decrease the colony formation ability or proliferation of ovarian, lung, breast, hepatocellular, and colorectal cancer cells." (PMID 36548179, 2022).
cancer (continued). "SOX2OT is mapped on a highly conserved region in chromosome 3q26.3 in humans and has various cellular functions in embryogenesis and neuronal development, cancer cell proliferation, metastasis, and drug resistance." (PMID 36548179, 2022). "Recent studies identified that SOX2OT expression is increased in many cancers." (PMID 34238205, 2021). "Abnormal expression of SOX2OT has been observed in various of cancers." (PMID 34238205, 2021). "SOX2OT is involved in various stages of progression of a malignant tumor." (PMID 29504701, 2018). "SOX2OT has been demonstrated to be aberrantly expressed in several types of cancer and maybe serve as a prognostic marker for cancer patients." (PMID 28489861, 2017). "Altogether, the overlapped expression of SOX2OT with SOX2, and the conserved association between them in different developmental systems of vertebrates, and also in human cancer and stem cells all support the existence of a complex functional regulatory relationship." (PMID 26136768, 2015). "Interestingly, SOX2OT is differentially spliced into multiple mRNA-like transcripts in stem and cancer cells." (PMID 26136768, 2015). "Sox2OT was found to be crucial for the development and maintenance of the pluripotency of cancer stem cells (CSCs), while its dysregulation was reported in several cancers including osteosarcoma, glioblastoma, lung and breast cancer, and others, where it plays an oncogenic or tumor-suppressor role." (PMID 35455947, 2022). "In addition, SOX2OT itself may promote cancer progression through sponging miRNA-144-3p, which induces cell apoptosis and targets the c-MET oncogene." (PMID 36012529, 2022). "Interestingly, SOX2OT and ANRIL expressions have previously been linked with cancers by others." (PMID 29504701, 2018). "We found that SOX2OT expression decreases with tamoxifen resistance, and high levels of SOX2OT enhance the proliferation, invasion, and migration of TAMR cancer cells, yielding poor outcomes." (PMID 38649821, 2024). "SOX2OT also regulates the level of SOX2 transcription factor, which plays a key role in in maintaining the pluripotency of cancer stem cells." (PMID 36012529, 2022). "Activation by SOX2OT’s two signaling pathways (Wnt5a/β-catenin and PI3K/AKT/ERK) leads to inhibiting apoptosis and cancer progression." (PMID 36012529, 2022). "Patterns of concomitant expression of SOX2OT and SOX2 in stem cells and several human cancers suggest a common co‐regulation mechanism and involvement of similar molecular pathways." (PMID 30117678, 2018). "Other driver lncRNAs with frequent CNA promoted the growth of cancer cells, including BCAL8, and SOX2OT." (PMID 30216655, 2018). "Close concomitant expression patterns of SOX2OT and SOX2 in stem cells and some human cancers, have also highlighted the possibility that transcriptional regulation of SOX2 by SOX2OT." (PMID 28489861, 2017). "Furthermore, SOX2OT exerts regulatory function in cell cycle progression; hence its association with carcinogenesis of human tumors of breast, esophagus, and lung cancers is not surprising." (PMID 26136768, 2015). "Since the SOX2OT level was decreased in TAMR cell lines compared with that in the MCF7 cell in previous study, SOX2OT expression was intentionally increased to examine how this reduction affects actual TAMR cancer cells." (PMID 38649821, 2024). "Recent studies have provided evidence that SOX2OT plays a positive role in the transcriptional regulation of the SOX2 gene, and the dysregulation of SOX2OT expression has been highlighted in multiple cancers and CSCs." (PMID 32019566, 2020). "SOX2OT is over expressed in human cancer tissues of lung, esophagus and breast when comparing to normal and it’s over expression in tumors is associated with SOX2, which is located within SOX2OT." (PMID 30202240, 2018).